IFNG (interferon gamma)
Diseases named in the same sentence as IFNG in open-access papers (continued):
Sharing a sentence is not in itself a finding about the gene and the disease.
leukemia (190 papers, 2007 to 2026). A malignant (clonal) hematologic disorder, involving hematopoietic stem cells and characterized by the presence of primitive or atypical myeloid or lymphoid cells in the bone marrow and the blood. "Leukemia-specific cells are specifically triggered immune cells that produce interferon gamma (IFNg), tumor necrosis factor α (TNFα) or initiate cells’ degranulation in the presence of leukemia-associated antigens (LAA) like WT1 or PRAME." (PMID 41226377, 2025). "Last, the anti-leukemia activity of these memory-like NK cells was associated with increased IFNγ production and expression of the NK cells activation receptor NKG2D which promotes IFNγ production." (PMID 27816971, 2016). "To determine whether Fitm2 loss similarly sensitizes our leukemia cells to IFNγ, we generated Fitm2 KO cells and treated them with IFNγ in vivo and in vitro." (PMID 38052854, 2023). "Taking away the ATF4-mediated blockade, sorafenib allowed IRF7 activation and caused IL-15 transcription in the leukemia cells which caused an increase of CD8+ CD107a+ IFNγ+ T cells, which was connected to the increased elimination of leukemia cells by activated donor T cells." (PMID 35460465, 2022). "Moreover, it has also been demonstrated that IFNγ secreted by NK cells is involved in the induction of graft-versus-leukemia (GVL) effects in IFNγ-deficient allo-HCT models, while inhibits GVHD." (PMID 27816971, 2016). "Moreover, the anti-leukemia activity of these memory-like NK cells was associated with IFNγ production and up-regulation of NK cells activation receptor-NK Group 2 member D (NKG2D)." (PMID 27816971, 2016). "Moreover, the mechanism underlying anti-leukemia activity of these NK cells was associated with increased IFNγ secretion via up-regulation of NKG2D." (PMID 27816971, 2016). "DNTs are potent producers of IFNγ, and can migrate to the BM, the primary site of leukemia engraftment, and GvHD-prone tissues such as the liver." (PMID 39876025, 2025). "As a precursor of the auxin, tryptophol not only possesses hypnotic effect and reduces the production of Prostaglandin E2 (PGE2), TNFα, and IFNγ, but also inhibits the activity of butyrylcholinesterase and the proliferation of leukemia U937 cells." (PMID 38396889, 2024). "One possible explanation for this is observation is that NK cells are the source of IFNγ that induces Qa-1b on B-ALL cells in the in vivo leukemia microenvironment." (PMID 38052854, 2023). "Here, we analyzed urothelial (T24) cell line with respect to cytokine signaling by interferon γ (IFNG) and the leukemia lymphocyte (Jurkat) cell line with respect to T-cell activation as mimicked by phorbolester and calcium ionophore (pma/iono)." (PMID 37138100, 2023). "After a mixed lymphocyte culture enriched with patients’ T cells (MLC), the leukemia-specific antileukemic effects were assessed through the degranulation- (CD107a+ T cells), the intracellular IFNγ production- and the cytotoxicity fluorolysis assay." (PMID 38139264, 2023). "By directly interacting with leukemia stem cells (LSCs), human ILC1s can eliminate LSCs via production of IFNγ and block LSC differentiation into M2 macrophage-like, leukemia-supporting cells through TNF." (PMID 36711868, 2023). "A possible explanation for this result is that NK cells serve as an important source of IFNγ in the leukemia microenvironment allowing for increased tumor cell Qa-1b induction prior to and during CAR-T therapy, thus rendering the cells more resistant." (PMID 38052854, 2023). "Messenger RNA (mRNA) and interferon gamma (IFN-γ) levels of leukemia KHYG-1 cells increased when treated with a combination of Lactococcus lactis subsp." (PMID 36144335, 2022). "Since IFNγ promotes ICAM-1 expression on leukemia cells, HPC-NK cells were co-cultured overnight with K562 or THP-1 with or without N-803, whereupon ICAM-1 expression was analyzed." (PMID 33140189, 2021).
leukemia (continued). "In vitro and in vivo expression assays and engraftment with interferon gamma receptor-1 (IFNGR1) null mice and IFNG KO SCLL cells, showed the leukemia cells produced IFN-γ directly participating in the induction of MDSCs to establish immune evasion." (PMID 34906138, 2021). "Similar to leukemia, IFNγ production significantly increased by N-803, for HPC-NK cells with and without SKOV-3: median 1.5-fold for HPC-NK cells + SKOV-3, p < 0.01." (PMID 33140189, 2021). "CSPG4-CAR T cells exhibited antigen-dependent upregulation of activation markers and antigen-dependent IFNγ production in response to leukemia cells." (PMID 31195686, 2019). "Human IFI16, an ortholog of the mouse BC094916 gene, was shown to localize to the nucleus of 293T cells, lymphoma line Daudi cells, and IFNγ-treated cells of the leukemia line HL-60." (PMID 30220882, 2018). "Of the 22 cell lines evaluated, six showed a significant decrease in NK cell-mediated lysis after IFNγ treatment, including leukemia, EWS, lymphoma, and NB cells." (PMID 28428785, 2017). "The results of the current study found that the cytokine expression was variable among the assays which used BMSCs from three different donors; BMSCs from only one of the donors reacted to the leukemia cells by increasing the expression of IFNγ and CD40L." (PMID 24304929, 2013). "The analysis of all batches of anti-leukemia CTLs produced so far documented that the majority of effector cells were CD3+/CD8+ cells, with a memory/terminal activated phenotype displaying efficient capacity to lyse patients’ LB and to secrete IFNγ and TNFα in response to leukemia cells." (PMID 40547030, 2025). "In addition, MSCs interfered with the secretory potential of leukemia-associated WT1- and ROR1-targeting CTL clones, inhibiting the release of IFNγ, tumor necrosis factor alpha, and IL-2." (PMID 38231344, 2024). "Moreover, the cytolytic function of the PRAMEmTCRCAR-T cells was enhanced through the application of interferon gamma to the targeted leukemia cells because interferon gamma can increase PRAME antigen expression." (PMID 38596687, 2024). "However, CD19 loss is not significantly enriched in cell culture treatment with CAR-T cells, implicating indirect IFNγ-mediated cell death as the primary mechanism of in vitro leukemia cell death." (PMID 38052854, 2023). "Besides, blockage of TIGIT significantly increased IFNγ production and NK cell degranulation, contributing to NK cells mediated anti-leukemia effects." (PMID 36605439, 2022). "Data on anti-leukaemia activity were also corroborated by the quantification of inflammatory cytokines, namely granzyme B (Granz B), interferon gamma (IFN-γ) and tumour necrosis factor alpha (TNF-α), both in vitro and in the plasma of mice treated with CAR.CD123-NK cells." (PMID 36335396, 2022). "The group of cell lines with decreased lysis after IFNγ treatment includes leukemia cell lines Molt-4 (p = 0.0030) and Kasumi-1 (p = 0.0231), EWS cell lines CHLA-9 (p = 0.0037) and CHLA-10 (p = 0.0292), lymphoma cell line Ramos-RA1 (p = 0.0007), and NB cell line CHLA-136 (p = 0.0065)." (PMID 28428785, 2017). "Nevertheless, it is noteworthy that both IFNγ and NKG2D might be involved in the mechanism of action underlying anti-leukemia activity of NK cells induced by in vivo IL pre-activation and re-stimulation." (PMID 27816971, 2016). "In addition, TNFα stimulation is necessary for maximal IFNγ-induced suppression and proliferation of leukemia cell cultures, further emphasizing the potential for IFNγ to elicit distinct and even opposing effects dependent on the local cytokine milieu." (PMID 27621733, 2016). "Furthermore, it has been shown that human IFNγ produced by genetically modified MSCs was able to inhibit proliferation and induce apoptosis of human leukemia K562 cells in vitro." (PMID 25428727, 2014).
leukemia (continued). "More importantly, when immature Fast DC were transfected with mRNA isolated from Jurkat E6 leukemia cell line, which was used as a tumor model, T cells specific for transfected DCs were readily picked up in the IFNγ ELISPOT assay after one single cycle of in vitro stimulation of autologous T cells." (PMID 17608923, 2007). "Therefore, while DNTs relied on IFNγ and TNFα to promote the anti-leukemic activity of Tconv cells, they may also promote recruitment of Tconv cells to the site of leukemia engraftment in vivo via the release of chemokines." (PMID 39876025, 2025). "Thus, this study provide evidence supporting a notion that NK cells characterized by CD56dim, NKG2C+ and self-KIR+ expand and persist in response to CMV reactivation in patients after haplo-HSCT, which in turn produce IFNγ to control CMV infection as well as prevent leukemia relapse." (PMID 27980216, 2017). "The present results indicated that IFNγ is functionally involved in the mechanism of action for NK cells induced by in vivo IL pre-activation and re-stimulation to kill leukemia cells, consistent with the previous finding that NK cells act against leukemia cells via IFNγ secretion." (PMID 27816971, 2016). "We therefore analyzed the effects of IFNγ and Senexin B in a known IFNγ-responsive cell line, HAP1 leukemia." (PMID 37378433, 2023). "Downregulation of HIF1α, oxidative phosphorylation, and PI3kinase pathways at EOI along with the regulators IFNG, TNF, VEGFA, IL1B in B cells is likely to impede leukemia supportive pro-inflammatory signaling." (PMID 37532715, 2023). "Collectively, these data show that N-803 boosts IFNγ production by HPC-NK cells, promotes ICAM-1 expression on leukemia cells and improves HPC-NK cell-mediated leukemia killing." (PMID 33140189, 2021). "We found that N-803 can increase IFNγ production of HPC-NK cells and augment HPC-NK cell-mediated killing of OC and leukemia cells in vitro." (PMID 33140189, 2021). "To explore the direct role of leukemia cell derived IFN-γ in immune evasion, we used CRISPR/Ca9 to create IFNG KO clones in the BBC2 cells and generated two complete KO clones that are confirmed at both the protein (above) and genomic DNA (below) levels." (PMID 34906138, 2021). "CSPG4-CAR T cells produced significantly more IFNγ than control CEA-CAR T cells and mock T cells upon co-culture with KOPN8 leukemia cells." (PMID 31195686, 2019). "Beneficial effects of adjuvant treatment using IFNγ for fungal infections in patients suffering from chronic granulomatous disease HIV, leukemia, and in organ transplant patients were previously reported." (PMID 31690258, 2019). "When stratified by tumor type, we observe that PD-L1 was most upregulated by IFNγ in solid tumor cell lines (RMS, brain, EWS, and NB), but was relatively unaffected on leukemia and lymphoma cell lines." (PMID 28428785, 2017). "Interferon gamma (IFNγ) is an efficient inducer of immunoproteasome expression and partly restored BTZ sensitivity in BTZ-resistant leukemia cells." (PMID 29071527, 2017). "Frequencies of uncultured and leukemia-specific (degranulating or IFNγ-producing) immunoreactive cells with or without LAA (WT-1 and PRAME) stimulation were comparable in WB vs. WBM." (PMID 38139264, 2023). "Finally, altered expressions of CD28, CCR7, CX3CR1, IFNG, LTB and PRF1 were all contributing to the inflammatory profile of the TCRγδ+ T-LGL leukemias." (PMID 28407008, 2017). "Strikingly and in line with STAT3β-deficient leukemia cells displaying attenuated commitment to the myeloid lineage, a significant decrease in CD11b expression and an increase of LSK blasts was detected upon IFNγ stimulation, which was stronger in leukemia cells lacking STAT3β." (PMID 38806478, 2024). "However, combined inhibition of TIGIT, PD-1, and Tim-3 significantly up-regulated IL-2, IFNγ, and TNFα in both CD4+ and CD8+ T cells, which may enhance anti-leukemia immune responses." (PMID 36605439, 2022).
leukemia (continued). "It was also shown that the NK cell-mediated cytotoxicity was strictly NKG2D dependent because control constructs lacking the ULBP2 domain could not induce IFNγ secretion and killing activity of co-incubated NK cells in response to leukemia cells." (PMID 28943878, 2017). "In summary, the present study provided the bulk of evidence indicating that in vivo IL pre-activation and re-stimulation can generate memory-like NK cells with enhanced IFNγ production, which might represent a novel approach for the NK cell ACT therapy to treat cancer like leukemia." (PMID 27816971, 2016). "In conclusion, our findings could constitute a definitive proof of the relation, occurring in leukemia microenvironment, between IDO1 induction on AML blasts mediated by NK cell-produced IFNγ and the consequent functional deregulation of NK cells that favors AML immune escape." (PMID 25886742, 2015). "It is known that progenitor cells (CD34+) in the bone marrow may express Fas in response to tumor necrosis factor-alpha (TNF-α) and interferon-gamma (INF-γ) in vitro and cytotoxic T lymphocytes in T-LGL leukemia may spontaneously produce INF-γ and TNF-α after stimulation." (PMID 18474096, 2008). "Next, we stimulated HPC-NK cells with leukemia cell lines K562 or THP-1 for 4 h with or without N-803 and analyzed IFNγ production." (PMID 33140189, 2021). "On the other hand, the adhesion molecule ICAM-1 was upregulated by IFNγ on brain tumors, EWS, NB, and leukemia, but not on RMS and lymphoma cells." (PMID 28428785, 2017). "Additionally, CSPG4-CAR T cells did not secrete IFNγ upon co-incubation with T2.A1 cells, confirming antigen-specific IFNγ secretion towards CSPG4-positive KOPN8 leukemia cells." (PMID 31195686, 2019).
vitiligo (185 papers, 2005 to 2026). Generalized well circumscribed patches of leukoderma that are generally distributed over symmetric body locations and is due to autoimmune destruction of melanocytes. "ELISAs showed that inflammatory cytokines associated with vitiligo, such as IFNγ, IL6, and CXCL10 were significantly elevated in CUMS serum." (PMID 40361040, 2025). "T‐cell activation was analyzed by the increased expression of the activation marker CD137 and by the production of cytokines TNFα and IFNγ, which are associated with a type 1 T‐cell response often observed in vitiligo." (PMID 30767390, 2019). "By performing scRNAseq on vitiligo patient biopsies and experimental vitiligo mouse models with Ifngr1-deficient Pdgfra+ fibroblasts, Xu and colleagues found that fibroblasts activated by IFNγ mediate CD8 T cell recruitment underlying autoimmune depigmentation." (PMID 36591258, 2022). "Furthermore, vitiligo NK cells are much more sensitive to stress, produce much larger amounts of IFNγ following stress, and are directly implicated in initiation of long-term adaptive immunity against melanocytes." (PMID 33936032, 2021). "Recent advances underscore the centrality of the interferon-gamma (IFN-γ)–JAK–STAT pathway activation in vitiligo pathogenesis." (PMID 41454839, 2026). "IFNγ, generated by NK and ILC1 cells, was associated with higher levels of CXCL9 (p = 0.018) and CXCL10 (p = 0.02) proteins in the supernatant of vitiligo melanocytes, equivalent to an average 4- to 5-fold increase in chemokine production compared to controls." (PMID 39861486, 2025). "The present data contribute to confirming the relevant role of the IFNγ/CXCL10 axis in the pathogenesis of vitiligo, highlighting CXCL10 as a possible activity marker." (PMID 37985303, 2024). "Meanwhile, autoreactive CD8 + T lymphocytes drawn to proinflammatory cytokines are thought to facilitate melanocyte death in vitiligo by killing the pigment-producing cells of melanocytes via interferon-gamma (IFN-γ) signaling." (PMID 38695020, 2024). "Another important factor in the relationship between vitiligo and prostate cancer is the mechanism of interferon-gamma (IFN-γ)." (PMID 38817459, 2024). "In this line of work, JAK inhibitors that block the IFNγ signaling pathway have shown to be promising for some dermatological diseases such as atopic dermatitis, alopecia areata, and vitiligo." (PMID 37985303, 2024). "Recent research indicates that vitiligo patients have altered immune responses and increased stress-induced production of Interferon-gamma (IFN-γ), which leads to melanocyte apoptosis." (PMID 38136732, 2023). "The cyclical nature of the feedforward loop leads to the progressive aggregation of CD8+ T cells in areas with IFNγ-responsive fibroblasts resulting in the development of vitiligo." (PMID 35950754, 2022). "One study showed that IL15 causes the expression of NKG2D in memory CD8 + T Cells in skin with vitiligo, triggering the production of IFNγ and TNFα." (PMID 35643735, 2022). "Autoreactive CD8+ T lymphocytes produce interferon-gamma (IFN-γ), as demonstrated by its increased levels in vitiligo lesions." (PMID 35884944, 2022). "Analysis of the transcriptional profile of lesional vitiligo skin demonstrated an IFNγ-specific signature." (PMID 36359263, 2022). "The Janus kinase/signal transducers and transcription activators (JAK/STAT) pathway participate in the immunopathogenesis of vitiligo through its interaction with IFNγ." (PMID 35643735, 2022). "Janus kinase inhibitors have been demonstrated to decrease interferon-gamma signaling, which aids in the re-pigmentation of vitiligo patients." (PMID 36475210, 2022). "The results of this study highlighted the essential role of IFNγ-responsive fibroblasts in the immune responses in vitiligo, which shed light on the potential role of fibroblast-targeting therapies." (PMID 35950754, 2022).